PYGL (glycogen phosphorylase L)
Diseases named in the same sentence as PYGL in open-access papers (continued):
Sharing a sentence is not in itself a finding about the gene and the disease.
cancer (19 papers, 2014 to 2025). A tumor composed of atypical neoplastic, often pleomorphic cells that invade other tissues. "From the GTEx database, we found that the PYGL eGene was associated with the risk of cancer development." (PMID 35204406, 2022). "Our results further demonstrated that high PYGL expression was closely associated with infiltration of immune cells in tumors, with this expression pattern also positively correlated with cancer associated fibroblasts (CAFs)." (PMID 35111740, 2021). "In a recent report, the depletion of PYGL resulted in irreversible glycogen accumulation that was associated with a reduced proliferation and a corresponding induction of senescence in cancer cell lines." (PMID 25051373, 2014). "Glycogen degradation by PYGL serves as an important pathway for metabolic reprogramming in cancer cells because it modulates the optimal function of PPP and thereby cellular fate." (PMID 40263302, 2025). "Favaro reported that glucose utilization via PYGL sustains cancer cell proliferation and prevents premature senescence." (PMID 38483604, 2024). "The present study explored the GEPIA database to investigate the expression levels and functions of HPRT1 and PYGL in multiple cancer types." (PMID 37371537, 2023). "IHC staining also showed that PYGL was predominantly localized in the cytoplasm and nucleus of both cancer cells and normal pancreas cells." (PMID 37063425, 2023). "For example, PYGL catalyzes the key step of glycogen degradation, and its depletion leads to consequent glycogen accumulation in cancer cells." (PMID 32802186, 2020). "Colon Transverse PrediXcan analyses were repeated for TRIM4 and PYGL in the discovery dataset stratifying cases by proximal (n = 4454 cases), distal (n = 3580 cases), and rectal (n = 2936 cases) cancer sites." (PMID 30820706, 2019). "However, few studies on the roles of PYGL in cancer are so far available, and PYGL has an unclear function in PDAC." (PMID 37063425, 2023). "So far, the expression pattern of PYGL and its clinical significance in human cancers remain unclear." (PMID 37063425, 2023). "Overall, these findings suggested that HPRT1 and PYGL might play important roles in cancer development and prognosis." (PMID 37371537, 2023). "It was also believed that the degradation of glycogen, which is regulated by PYGL, could sustain proliferation and prevent premature senescence in cancer cells." (PMID 38293671, 2023). "The glycogen degradation mediated by PYGL has been hypothesized to sustain the growth of cancer cells." (PMID 36699685, 2022).
cardiovascular diseases (1 paper, 2023). "Hence, PYGL could serve as a therapeutic target for CKD, MI and/or other renal/cardiovascular diseases." (PMID 37123453, 2023).
metabolic disorders (1 paper, 2022). "Through SELENOF and AKT1/FOXO3a/PYGL, selenium-containing agents regulate glucose and lipid homeostasis in the liver, preventing metabolic disorders." (PMID 35743086, 2022).
PYGL also shares sentences with these, for which no sentence is quoted: head and neck squamous cell carcinoma (3 papers); seminoma (3); Hepatic fibrosis (2); Obesity (2); papillary renal cell carcinoma (2); asthma (1); atherosclerosis (1); brain tumour (1); cervical adenocarcinoma (1); Cirrhosis (1); clear cell renal cell carcinoma (1); Dyskinesia (1); familial intrahepatic cholestasis (1); hyperlipidemia (1); hyperuricemia (1); injury (1); Insulin resistance (1); rheumatoid arthritis (1); sarcopenia (1); skin aging (1); type 2 diabetes (1).